IRF3 (interferon regulatory factor 3)
Diseases named in the same sentence as IRF3 in open-access papers (continued):
Sharing a sentence is not in itself a finding about the gene and the disease.
infection (continued). "Later on, other studies supported the induction of a β-catenin-IRF3-p300/CBP complex upon infection with Sendai virus (SeV) and influenza A virus H1N1 that acts in parallel to the RLR-TBK1-IRF3 pathway to fine-tune the antiviral innate immune response." (PMID 32272583, 2020). "Our work suggests that an IRF5-dependent pathway acts locally in draining lymphoid tissue following infection with CHIKV, whereas IRF3/7-dependent pathways are activated at the site of inoculation." (PMID 31999809, 2020). "The cytoplasmic ICP0 inhibited IRF3 activation and IRF3-dependent ISG induction at later stages of infection." (PMID 32317666, 2020). "The early phosphorylation of IRF3 and IRF7 was particularly triggered by infection with the pde2 mutant, implicating this pathway in the select responses of macrophages to these Δpde2 bacteria." (PMID 32300347, 2020). "This indicates the critical role that IRF3 and IRF7 play in not only activating the type I IFN response at early stages of infection, but also in controlling these IFN levels to prevent neurotoxicity." (PMID 32708188, 2020). "The expression levels of zbTRIM25 and its downstream genes, RIG-I, MAVS, TRAF3, IRF3, and IFN 1 decreased to some different extent at 24 h post RGNNV infection in miR-202-5p mimics transfected ZBE3 cells." (PMID 32120903, 2020). "We found that fish MAVS acts as a crucial signaling molecule in the infection of SCRV, which mediated both the NF-κB and IRF3 activation and lead to type I IFNs and inflammatory cytokine production." (PMID 32678830, 2020). "Overexpression of MG53, in the presence of RyR, suppressed the activity of both IRF3 and NFκB following SeV infection, confirming the ability of MG53 to inhibit the IFN response to infection." (PMID 32681036, 2020). "On the contrary, we found that DAP12 overexpression in CRL-2843-CD163 cells suppressed p65 phosphorylation by reducing IκB-α degradation, as well as IRF-3 phosphorylation, during PRRSV early infection." (PMID 32093750, 2020). "Ultimately, Npro’s antagonism of TLR3-, RIG-I-, and IRF3-mediated apoptotic responses serves as another mechanism of CSFV immune evasion, likely contributing to the establishment of infection and host persistence." (PMID 33328306, 2020). "Compared with the normal control group, the expression levels of all proteins (TLR3, TAK1, TBK1, IRF3, and IFN-β) were increased after infection with influenza virus." (PMID 31975996, 2019). "Moreover, we also observed consistent phenomena in HSV-1-infected A549 cells with IFI16-/-, IFI16-/—STING knockdown or IFI16-/—cGAS knockdown, indicating that IFI204 might facilitate cGAS-STING DNA sensing pathway that leads to IRF3 activation during the infection of HSV-1." (PMID 31603949, 2019). "IRF3 is a critical interferon regulatory factor, which enters into the nucleus and drives IFN-β transcription after infection." (PMID 30791397, 2019). "The few cells that were able to proceed to the later stages of infection (as indicated by the appearance of replication compartments and cytoplasmic ICP4 foci) showed the same peri-nuclear aggregation of IRF3 as wildtype-infected cells." (PMID 31090537, 2019). "Although there were differences in induction of some ISGs (IFITM3, IRF3, ISG15, VIG1, and MX1), mRNA levels of type I IFNs were below the detection limit in pLNs or similar in spleens of B6 and CD169−/− mice post-FVC infection." (PMID 30595553, 2019). "We also found that infection with WT HSV-1 inhibited the dimerization of IRF3 induced by ISD, while infection with ΔUL46 HSV-1 resumed dimerization of IRF3 to a certain extent." (PMID 31113902, 2019). "Infection of a single (IRF3−/− and IRF7−/−) and double (IRF3/7−/−) knockout mice clearly demonstrates that either IRF3 or IRF7 is required for survival following CHIKV infection, with IRF3/7−/− mice showing significant viral dissemination with high titres." (PMID 30909385, 2019).
infection (continued). "Both TBK1 and IRF3 are subsequently activated and, in response to this, a high level of beta interferon (IFN-β) was produced during NH/P68 infection; in contrast, Armenia/07 infection generated IFN-β levels below those of uninfected cells." (PMID 30918080, 2019). "In the course of infection, SeV stimulated increasing amount of endogenous RIG-I expression, concomitant with increased levels of interferon regulatory factor 3 (IRF3) nuclear translocation." (PMID 30097581, 2018). "Firstly, infection with SA11-5S, which cannot degrade IRF3/7 and thus inhibit IFN-β expression due to a defective NSP1, induced higher bystander cell MHCI expression than infection with SA11-4F, which does degrade IRF3/7." (PMID 29311575, 2018). "These suppress viral replication and restrict infection through the activation and nuclear translocation of nuclear factor kappa B (NF-κB), IFN-regulatory factor 3 (IRF3), and IRF7, culminating in the expression of a variety of innate immune genes." (PMID 30241345, 2018). "As expected, cells deficient in Tbk1 or Irf3 appeared to have weaker levels of Tbk1 or Irf3 phosphorylation, respectively, indicating other pathways involved in Tbk1 or Irf3 were activated during the ECTV infection." (PMID 29963044, 2018). "It has been reported that the difference in rNDV infectivity between tumor cells and normal cells is responsive to IFN-β, the gene expression of RIG-I, IRF-3, IRF-7, and IFN-β before infection or the RIG-I gene and the receptor of type I IFN expression." (PMID 29882780, 2018). "Animal models for understanding the transmission and infection of ZIKV has been developed in the different strains of mice, such as AG129, C57BL/6, and Irf3/5/7 triple knockout (TKO) mice." (PMID 30356305, 2018). "In conclusion, we show that TBK1 spliced isoforms are important negative regulators which target TBK1 and IRF3 for disrupting the formation of the functional TBK1-IRF3 complex under physiological conditions and SVCV infection." (PMID 29441066, 2018). "Infection with the attenuated VACV strain MVA activated IRF-3 via cGAS and STING, and accordingly STING dimerized and was phosphorylated during MVA infection." (PMID 29491158, 2018). "Conversely, VACV strains Copenhagen and Western Reserve inhibited STING dimerization and phosphorylation during infection and in response to transfected DNA and cyclic GMP-AMP, thus efficiently suppressing DNA sensing and IRF-3 activation." (PMID 29491158, 2018). "Whereas MeV-vac2(GFP) infection induces minimal levels of PKR and IRF3 phosphorylation in standard HeLa cells, both antiviral pathways are strongly activated upon infection in p150KO and ADAR1KO cells." (PMID 30496178, 2018). "Prior to ACAM-2000 infection, keratinocytes were co-transfected with siRNA plus reporter plasmids directing luciferase expression under the control of NF-κB, IFN-β, or IRF3 promoter elements." (PMID 28081250, 2017). "The results indicated that both IRF3 and IRF7 were decreased at early time points but recovered to control levels at 24 h post-GCRV infection." (PMID 28396670, 2017). "Influenza virus can be recognized by RIG-I during infection and activates type-I interferon production by signaling transduction from RIG-I, MAVS, and TBK1/IKK-ξ complex to IRF3." (PMID 28392790, 2017). "In contrast, CCR2-DTR → Irf3-/-;Irf7-/- mice treated with PBS were protected against severe RRV disease, indicating that IRF3 and IRF7 sufficient hematopoietic cells can protect Irf3-/-;Irf7-/- mice against RRV-T48-nsP16M infection." (PMID 29244871, 2017). "Taken together, our data indicate that infection of GM-BM with ECTV inhibits nuclear translocation and sustained retention of NF-κB/p65, IRF3 and IRF7 in the nucleus induced by LPS treatment." (PMID 28604814, 2017). "In this study we examined the phosphorylation status of IRF3 and the kinetic profile of IFN gene/protein expression by Calu-3 cells after infection with recombinant H1N1 viruses carrying the S79L and/or K331N mutations." (PMID 28750037, 2017).
infection (continued). "To explore the lesions produced by acute infection with ZIKV in IRF 3/7 DKO mice, we infected a second group of IRF3/7 DKO females with the purpose of analyzing their tissues histologically." (PMID 28420392, 2017). "PIN1 and NF- κB mRNA levels were significantly downregulated after the infection, MHC-I, IRF3, and MAPK7 expressions were significantly upregulated following infection, whereas RMBX expression showed almost no variation." (PMID 29062054, 2017). "This was in full agreement with the observed inhibition of IRF3 nuclear translocation during virion and ISVP infection." (PMID 28883463, 2017). "For example, the roles of IRF3 and IRF7 in innate antiviral immunity against infection of West Nile Virus and dengue virus have been verified in previous studies." (PMID 27449021, 2016). "The MuHV-4 ORF36 inhibits IRF3 signalling, and ORF36- MuHV-4 delivered i.n. shows an IFNAR-dependent infection defect in lungs and spleens." (PMID 27223694, 2016). "We next investigated the transcription factors involved in the induction of IFN-β and asked if IRF3 was phosphorylated in IIV-6-infected cells, indicating the activation of this transcription factor during infection in both MEFs and A549 cells." (PMID 27824940, 2016). "β6 KO mTEC exhibited significant increases in total STAT1 and IRF3 levels as compared to WT mTEC after infection as well as at baseline, although differences in phosphorylated STAT1 and IRF3 were minimal." (PMID 27505057, 2016). "Treatment with coumermycin induced IRF3 phosphorylation in a manner equivalent to VVΔE3L infection, suggesting that activation of PKR is sufficient to activate IRF3." (PMID 26939124, 2016). "Disrupting the expression of PRR, IPS-1, IRF3, IRF7 and suppressing NF-κB significantly inhibited the production of IFN-β, IL-28A/B and IL-29 in the host following ATMUV infection." (PMID 27449021, 2016). "As infection progresses, ICP0 accumulates in the cytoplasm, where it antagonizes IRF3-mediated transactivation." (PMID 26937035, 2016). "Upon infection, SNRNP200 binds viral RNA and relocalizes into TBK1-containing cytoplasmic structures to promote IRF3 activation and IFNB1 production." (PMID 27454487, 2016). "This inhibition can be attributed to the fact that TMEV infection disallows the formation of IRF-3 dimers, which normally translocate to the nucleus to regulate transcription of antiviral genes (IFN-α/β as well as ISGs) in response to infection." (PMID 26150805, 2015). "The expression of MAVS, IRF-3/7, and type I interferons (IFN-α and IFN-β) are all altered post-infection." (PMID 26021751, 2015). "Whereas IRF3 is constitutively expressed at low levels and initiates IFN-I production after viral detection, IRF7 is an ISG that is expressed at high levels in infection and is the master regulator of the IFN-I response." (PMID 26709698, 2015). "After 8 days of intra-peritoneal injection of TORISEL (10mg/kg, injected every 2 days), irf3-/-/ irf7-/-mice were infected by CHIKV and tissues were analyzed at day 1 and 2 post-infection." (PMID 26317997, 2015). "We again observed more productive multiplication for Romero virus in IRF3/7 KO MEF cells (2.5×105 PFU/ml, 5 d.p.i.)than in wt MEF (2.3×104 PFU/ml, 5 d.p.i.), supporting the role of IFN pathway in suppressing JUNV infection in murine cells." (PMID 24901990, 2014). "Except for A5-16 where a truncated NSP1 is synthesized, infection with all other strains abrogated MAVS by almost 50% compared to the mock infected control, whereas IRF3 degradation was observed only in A5-13, EW and RRV strains." (PMID 24643253, 2014). "Upon infection, WNV delays IRF3 phosphorylation and nuclear translocation to allow for viral replication prior to the activation of anti-inflammatory genes." (PMID 25127040, 2014). "We found that MVA infection of Sting+/+ mice induces IFN-α and IFN-β production to the levels of 798 pg/ml and 1017 pg/ml, respectively, which was abolished in StingGt/Gt, and IRF3−/− mice." (PMID 24743339, 2014).
infection (continued). "Western blot analysis demonstrated that MVA-N1L infection triggered reduced levels of activation of p-TBK1 and p-IRF3 at 4 and 8 h post-infection when compared with MVA." (PMID 24743339, 2014). "This demonstrates that in contrast to IRF3 phosphorylation, which is delayed until 36 hours following WNV infection, NFκB signaling can be activated at early times post-infection and with it NFκB responsive mRNA and miRNA transcription." (PMID 25127040, 2014). "JEV-infected CHME3 cells showed increased phosphorylation of IRF3 as compared to controls; however, silencing of TRIM21 prior to infection further enhanced the phosphorylation and activation of IRF3." (PMID 24485101, 2014). "We found that infection with MVA-N1L virus induces lower levels of IFNA4 and IFNB mRNAs, as well as lower levels of p-TBK1 and p-IRF3." (PMID 24743339, 2014). "In contrast, as early as 8 h post-infection, IFN-β mRNA expression that is known to occur through activated IRF3, was enhanced by PMLIV leading to as high as a 2-log increase 12 h post-infection." (PMID 24586174, 2014). "Following infection, CTNNB1 is detected in the nucleus of SeV-infected HEK 293T cells, similarly to IRF3." (PMID 23785285, 2013). "After infection with MDV, the expression of IRF-3 gene was significantly higher in the thymus of the MDV-infected broilers when compared to that in the thymus of the control-uninfected broilers at 4 d.p.i (P = 0.0112) and 7 d.p.i (P = 0.0344)." (PMID 23710447, 2013). "We generated Irf3−/−×Irf5−/−×Irf7−/− triple knockout (TKO) mice and found that these mice were highly vulnerable to infection with WNV." (PMID 23300459, 2013). "Infection of the CEH with LPAIV induced an increase in DNA-binding transcription factors, c-Jun, p50 and IRF-3, most notably with trypsin supplementation." (PMID 24252391, 2013). "We previously reported that DENV serotype 2 (DENV-2) induced low levels of interferon regulatory factor 3 and NF-κB activation, thus leading to reduced production of IFN-β in the early phase of infection." (PMID 22927911, 2012). "In the prototypic antiviral response, IRF3 and early production of type I IFN and ISGs are arguably the most important events in combating infection." (PMID 22363706, 2012). "In summary, we identified sites of TBK1 ubiquitination in response to infection with RNA viruses and proposed a mechanism for assembly of a RLR-induced molecular complex responsible for IRF3 signal propagation." (PMID 23028469, 2012). "This has been observed during the response of mice to infection with vaccinia virus, where a subset of Ly6Chi inflammatory monocytes produces type I IFN in an IRF3 and IRF7-dependent manner after TLR2-mediated recognition of viral ligands." (PMID 22815909, 2012). "The contribution of IRF5 as well as IRF3 and IRF7 activation by IAV during infection and MDP treatment is the subject of ongoing investigation." (PMID 22590599, 2012). "The small molecule DMXAA activates multiple immune pathways (NF-κB, TBK1/IRF3, NOD, and MAP kinase) but was ineffective as an antiviral unless it was administered before infection." (PMID 22574190, 2012). "Altogether, these data revealed that, during infection with the WT VZV, the viral kinase ORF47p is responsible for the decrease of IRF3-dependent genes expression." (PMID 21347389, 2011). "For examples, ISGylation of RIG-I negatively regulates RIG-I signaling and leads to a reduction of IFN production; while ISGylation of IRF3 prevents the ubiquination and degradation of IRF3 during DNV infection." (PMID 21992229, 2011). "To address if this PLP2 domain containing protein was also in the complex of TBK1-IRF3, we then overexpressed Flag-IRF3 in HEK293T-mCEACAM-1 cells or 17Cl-1 cells before MHV-A59 infection." (PMID 21364999, 2011). "Cellular localization of IRF3 and IRF7 was analyzed by immunofluorescence at different times post-infection." (PMID 22206025, 2011).
infection (continued). "Upon infection with WT HSV-1 (strain F), nuclear IRF3 dimers were observed at 4 and 6 hours post-infection (hpi) but diminished at later times." (PMID 20454685, 2010). "Following infection with a corresponding ICP0-null HSV-1 (R7910), IRF3 dimerization and nuclear translocation were sustained up to 8 hours." (PMID 20454685, 2010). "With respect to IRF3 activation, infection with D8 and R7914 mirrored that of WT and ICP0-null virus, respectively, in that IRF3 phosphorylation, dimerization and nuclear translocation were inhibited by cytoplasmic ICP0 only." (PMID 20454685, 2010). "In summary, these results demonstrate that upon infection with WT HSV-1, IRF3 is activated but is subsequently inhibited by ICP0 at a time point that correlates with its cytoplasmic localization." (PMID 20454685, 2010). "Expression of IRF3, TBK-1, IKKε, DDX3 or HSP90 remain unchanged by the presence of ICP0 during infection." (PMID 20454685, 2010). "In contrast, IRF-3−/− MEF had a diminished IFN-α and -β response early after infection but developed normal levels at later time points (S. Daffis and M. Diamond, unpublished data)." (PMID 19798431, 2009). "In this study, using a mouse model of WNV infection, we evaluate the combined role of two key transcription factors, interferon-regulatory factor-3 (IRF-3) and IRF-7, that orchestrate antiviral and interferon (IFN) responses after infection." (PMID 19798431, 2009). "In contrast, infection with SA11-5S, which expresses a C-truncated NSP1, led to little decrease in IRF3 levels." (PMID 21994581, 2009). "Contrary to IRF3, recruitment of CBP normally observed after C13 infection was inhibited after ZH infection." (PMID 18225953, 2008). "In this study, using a mouse model of WNV pathogenesis, we evaluate the functional role of interferon regulatory factor 3 (IRF-3), a master transcriptional regulator of interferon induction and antiviral responses, in controlling infection." (PMID 17676997, 2007). "Kinetic analysis of IFN gene induction also showed markedly higher (12- to 55-fold) IFN-β levels compared to IFN-α levels at 24 to 48 h after infection in wild-type neurons and blunted IFN transcript levels in WNV-infected IRF-3−/− neurons." (PMID 17676997, 2007). "Our results in IRF-3−/− macrophages agree with studies of IRF-3−/− splenic dendritic cells, which showed relatively normal IFN induction after infection with VSV or HSV." (PMID 17676997, 2007). "In contrast, IRF-3−/− cortical neurons, which had blunted production of IFN, also had markedly lower levels of IRF-7 mRNA after infection." (PMID 17676997, 2007). "In contrast, conditioned media from IFNλ2/3 KO and IRF3 KO cultures failed to provide this protection, resulting in markedly higher infection levels compared to cells treated with WT media." (PMID 41525418, 2026). "Given that both SVCV-P and IRF3 independently possess LLPS capabilities, we are prompted to explore the interplay between TBK1 phase separation events driven by SVCV-P and those triggered by IRF3 during a genuine SVCV infection." (PMID 41363845, 2026). "The transcript and protein levels of IFN-α, IFN-β, RIG-I, MDA5, MAVS, TRAF3, TBK1, and IRF3 in the PRRSV-infected cell group by anti-FcγRI IgG pre-treatment were significantly declined at 12 h and 24 h post-infection compared to those in the PRRSV-infected cell group by RNI pre-treatment." (PMID 41012704, 2025). "Interestingly, phosphorylation of IRF3 increased between 4 and 8 h post-ASFV infection and gradually decreased thereafter, while phosphorylation of STAT1 continued to rise up to 24 h." (PMID 40500801, 2025). "However, the levels of other innate immune signaling proteins, such as JAK1, STAT1, p-STAT1, IRF3, or IRF1, remained similar after infection with UL88-STOP or WT TB40/E." (PMID 40638072, 2025). "Infection with H. pylori PMSS1 strain significantly decreased the levels of total and phosphorylated IRF3 proteins, concomitant with a suppression in mRNA expression of IRF3." (PMID 39924917, 2025).